MED19 (mediator complex subunit 19)
Description:
Component of the Mediator complex, a coactivator involved in the regulated transcription of nearly all RNA polymerase II-dependent genes. Mediator functions as a bridge to convey information from gene-specific regulatory proteins to the basal RNA polymerase II transcription machinery. Mediator is recruited to promoters by direct interactions with regulatory proteins and serves as a scaffold for the assembly of a functional preinitiation complex with RNA polymerase II and the general transcription factors.
Synonyms: LCMR1; DT2P1G7; MED19AS
Tractability: Small molecule: a structure with a bound ligand is known. PROTAC: its protein half-life has been measured.
Gene: Protein-coding gene on chromosome 11 (57,703,710 to 57,712,259, reverse strand). Ensembl gene ENSG00000156603.
Subcellular location: Nucleus
Subcellular location (Human Protein Atlas): Nuclear bodies; Nucleoplasm
Pathways (Reactome):
Developmental Biology: Transcriptional regulation of white adipocyte differentiation
Disease: RSV-host interactions
Metabolism: PPARA activates gene expression
Gene Ontology:
Molecular function: protein binding; transcription coregulator activity
Biological process: positive regulation of transcription by RNA polymerase II; positive regulation of transcription elongation by RNA polymerase II; positive regulation of transcription initiation by RNA polymerase II; RNA polymerase II preinitiation complex assembly; regulation of transcription by RNA polymerase II
Cellular component: core mediator complex; nuclear body; nucleoplasm; nucleus; mediator complex
Genetic constraint (gnomAD): Loss-of-function variants: 4 observed, 18.38 expected, observed/expected ratio (o/e) 0.22, 90% interval 0.11 to 0.5. The synonymous counts are far from expectation, so gnomAD's model fits this gene poorly and the ratio says little. Missense variants: 303 observed, 296.6 expected, observed/expected ratio (o/e) 1.02, 90% interval 0.93 to 1.12. Synonymous variants: 139 observed, 109.81 expected, observed/expected ratio (o/e) 1.27, 90% interval 1.1 to 1.46.
Homologues: Orthologues: chimpanzee MED19 (99% identical), macaque MED19 (99% identical), pig MED19 (96% identical), rabbit MED19 (96% identical), dog MED19 (95% identical), guinea pig MED19 (95% identical), rat Med19 (95% identical), mouse Med19 (95% identical), zebrafish med19b (68% identical), tropical clawed frog med19 (66% identical), zebrafish med19a (64% identical), Drosophila melanogaster MED19 (39% identical), and 1 more.
Diseases named in the same sentence as MED19 in open-access papers:
MED19 is named in the same sentence as 33 diseases in open-access papers, as found by Europe PMC text mining. Sharing a sentence is not in itself a finding about the gene and the disease. The quoted sentences say what the papers report.
prostate carcinoma (11 papers, 2014 to 2024). A carcinoma that arises from epithelial cells of the prostate gland. "Indeed, we previously reported that overexpression of alternative MED19 in androgen-dependent prostate cancer cells caused early-stage androgen-dependent prostate cancer cells to become androgen-independent by modifying AR-dependent gene expression." (PMID 37880276, 2023). "Consequently, the upregulation of MED19 isoforms confers phenotypes associated with prostate cancer progression by altering gene expression." (PMID 37880276, 2023). "Some Mediator complex subunits, such as MED1 and MED19, are cofactors of AR and enhance its transcriptional activity in prostate cancer." (PMID 39253786, 2024). "For instance, CARM1 is found to be overexpressed in breast cancer and prostate carcinoma, mediator complex subunit 19 (MED19) is upregulated in bladder cancer, and nuclear receptor co-activator 5 (NCOA5) expression is elevated in colorectal cancer." (PMID 39343952, 2024). "Our group and others have established the significance of MED19 in prostate cancer cell proliferation." (PMID 37880276, 2023). "Taken together, our findings suggest that MED19 isoforms are co-expressed in prostate cancer and other types of cancer." (PMID 37880276, 2023). "MED19, a component of the mediator complex and a co-regulator of the androgen receptor (AR), is pivotal in prostate cancer cell proliferation." (PMID 37880276, 2023). "This study marks the first characterization of MED19 isoforms in cancer, shedding light on their distinct functions in prostate cancer." (PMID 37880276, 2023). "Here we demonstrate that MED19 generates two protein isoforms, each influencing gene expression differently and fostering prostate cancer cell growth and tumorigenesis in conditions of low androgen." (PMID 37880276, 2023). "This study investigated the effects of canonical MED19 overexpression on prostate cancer cell proliferation, tumor growth, and gene expression." (PMID 37880276, 2023). "Our research establishes, for the first time, the presence of MED19 isoforms at the protein level and illuminates their singular roles in the progression of prostate cancer." (PMID 37880276, 2023). "Our findings suggest that MED19 isoforms play unique roles in prostate cancer progression and highlights MED19 as a potential therapeutic target for both early and late-stage prostate cancer." (PMID 37880276, 2023). "This suggests that multiple prostate cancer cell lines express both MED19 protein isoforms, mirroring the expression pattern observed in prostate tissue." (PMID 37880276, 2023). "This corroborates the growth advantage of canonical MED19 found in LNCaP cells and demonstrates that the overexpression of canonical MED19 is sufficient to promote androgen-independent and androgen-dependent prostate cancer cell proliferation." (PMID 37880276, 2023). "Conversely, alternative MED19 levels were higher in later-stage metastatic prostate cancer than in canonical MED19, reflecting alternative MED19’s capability to enhance cell migration and autonomous cell growth." (PMID 37880276, 2023). "Our results indicate that increased levels of canonical MED19 led to enhanced prostate cancer cell proliferation and tumor growth in low androgen conditions, resembling the impact observed with alternative MED19." (PMID 37880276, 2023). "Although the regulation of gene expression and cancer cell characteristics by Mediator subunits is complex, our study provides key insight into the mechanism of MED19 action in prostate cancer cells and androgen independence." (PMID 33513133, 2021). "To determine if MED19 is sufficient to convert androgen-dependent prostate cancer cells to androgen independence, we stably overexpressed MED19 by lentiviral transduction in the prototypical androgen-dependent LNCaP cell line (MED19 LNCaP cells)." (PMID 33513133, 2021). "From this, we proposed that upregulation of MED19 in prostate cancer cells drives AR activity and androgen independence." (PMID 33513133, 2021).
prostate carcinoma (continued). "This study provides important insight into the mechanisms of prostate cancer cell growth under low androgen, and underscores the importance of the MED19-MAOA axis in this process." (PMID 33513133, 2021). "This demonstrates that expression of MED19 is sufficient to promote androgen independence in prostate cancer cells." (PMID 33513133, 2021). "A recent whole-genome, RNAi-based screen identified Med19 as an important element of Androgen Receptor activity in prostate cancer cells where gene expression levels also correlated with clinical outcome." (PMID 24786462, 2014). "We investigated whether the upregulation of canonical MED19 provided a proliferative advantage to prostate cancer cells." (PMID 37880276, 2023). "Further studies are required to understand the regulation of MED19 expression in prostate cancer." (PMID 37880276, 2023). "The ratio of MED19 isoform expression in prostate cancers shifts with the disease stage." (PMID 37880276, 2023). "However, the roles of canonical MED19 in prostate cancer cell proliferation and gene regulation remain undetermined." (PMID 37880276, 2023). "Therefore, MED19 is crucial in controlling specific gene subsets and directs prostate cancer survival and proliferation by regulating AR transcriptional activity." (PMID 37880276, 2023). "Therefore, we pursued gene targets occupied by MED19 and AR with an established connection to AR, preferably AR target genes, and known to play a role in prostate cancer proliferation." (PMID 33513133, 2021). "Here, we demonstrate that a subunit of the Mediator transcriptional regulatory complex, called MED19, promotes growth of prostate cancer cells under low androgen conditions, mimicking the ability of tumors to grow under androgen deprivation in prostate cancer patients." (PMID 33513133, 2021). "We also examined if upregulation of MED19 could promote the proliferation of other early stage prostate cancer cell lines." (PMID 33513133, 2021). "Moreover, a few studies found that MED1/17 and MED19 were extremely expressed in prostate cancer and breast cancer." (PMID 34649520, 2021). "However, the ratio of canonical MED19 to alternative MED19 mRNA expression is higher in early-stage primary cancers, including prostate, whereas the ratio of alternative MED19 versus canonical MED19 is higher in later-stage prostate cancer metastasis." (PMID 37880276, 2023). "Consequently, the genes and pathways influenced by canonical MED19 overexpression in LNCaP cells under androgen deprivation differ from those governed by alternative MED19, providing complementary oncogenic properties to prostate cancer cells." (PMID 37880276, 2023). "Additionally, we employed MED19 isoform-specific antibodies developed in our laboratory to explore the expression patterns of canonical MED19 and alternative MED19 proteins in prostate development, normal adult prostate tissue, and prostate cancer." (PMID 37880276, 2023). "MED19 overexpression also did not induce expression of AR-V7, a constitutively active splice variant of AR lacking the ligand binding domain that can drive androgen independence in prostate cancer." (PMID 33513133, 2021). "Across all cancer types, including prostate cancer (PRAD-red box), canonical MED19 is the more highly expressed isoform." (PMID 37880276, 2023). "This suggests that MED19 cooperates with ELK1 to regulate AR occupancy and H3K27 acetylation at MAOA, upregulating its expression and driving androgen independence in prostate cancer cells." (PMID 33513133, 2021). "Strikingly, MED19 upregulates expression of monoamine oxidase A (MAOA), a factor that promotes prostate cancer growth." (PMID 33513133, 2021). "MED19 promotes androgen-independent growth by working with a transcription factor that interacts with AR, called ELK1, to induce the expression of genes regulated by AR that promote prostate cancer growth." (PMID 33513133, 2021).
breast carcinoma (9 papers, 2017 to 2024). "Further, MED19 promoted breast cancer cell proliferation through the EGFR/MEK/ERK signaling pathway." (PMID 35047403, 2021). "Interestingly, LCMR1 (MED19) reportedly down-regulates C-X-C motif chemokine ligand 11 (CXCL11) in breast cancer; blocking LCMR1 contributes to high CXCL11 levels and positively correlates with antitumor immune responses." (PMID 38001705, 2023). "In breast cancer, Med19 may promote cell proliferation by regulating CBFA2T3/HEB expression." (PMID 28125713, 2017). "Using TIMER 2.0, MED19 was shown to be highly expressed for bladder urothelial carcinoma (BLCA), breast cancer (BRCA), liver hepatocellular carcinoma (LIHC), lung adenocarcinoma (LUAD) and other types in the TCGA project." (PMID 35047403, 2021). "Reportedly, mediator complex subunit 19 (Med19) interacts with EGFR and increases its expression; it activates the EGFR/MEK/ERK pathway and exerts its oncogenic activity in an EGFR-dependent manner in breast cancer." (PMID 33909822, 2021).
lung carcinoma (7 papers, 2011 to 2023). "For example, reduction of MED19 by siRNA has been reported to reduce the proliferation of certain breast, ovarian, cervical, and lung cancer cell lines, and increased abundance of MED19 protein is observed in tumors compared to benign tissue." (PMID 33513133, 2021). "In lung cancer, MED19 could promote tumor proliferation, tumorigenesis, metastasis, and enhance chemo-sensitivity to cisplatin in non-small cell lung cancer cells." (PMID 28125713, 2017).
osteosarcoma (5 papers, 2017 to 2024). A usually aggressive malignant bone-forming mesenchymal neoplasm, predominantly affecting adolescents and young adults. "The Med19 has been reported to promote tumor growth and/or metastasis in ovarian cancer, gastric cancer, pancreatic cancer, osteosarcoma, and liver cancer." (PMID 28125713, 2017).
bladder cancer (4 papers, 2017 to 2024). "MED19 knockdown inhibited the proliferation and migration of bladder cancer cells by down-regulating the WNT/β-catenin signaling pathway." (PMID 35047403, 2021). "Mediator complex subunit 19 (Med19), a RNA polymerase II‐embedded coactivator, is reported to be involved in bladder cancer (BCa) progression, but its functional contribution to this process is poorly understood." (PMID 28631286, 2017). "The expression of BMP6, a key endogenous regulator of iron metabolism, was affected by Med19, which could promote bone metastasis and invasiveness of bladder cancer." (PMID 35265613, 2022).
bladder urothelial carcinoma (2 papers, 2017 to 2021). "In addition, studies have reported that the expression of MED19 was positively correlated with the expression of bone morphogenetic protein 2 (BMP2) in bladder urothelial carcinoma bone metastasis and invasion." (PMID 35047403, 2021).
gastric cancer (2 papers, 2015 to 2017). A primary or metastatic malignant neoplasm involving the stomach. "Recently, it was reported that a MED19 can participate in gastric cancer progression, as its knockdown significantly inhibited cell proliferation and colony-formation capacity, and induced G1 phase cell-cycle arrest in two human gastric cancer cell lines (SGC7901 and MGC803)." (PMID 26110885, 2015).
leiomyoma (1 paper, 2013). A well-circumscribed benign smooth muscle neoplasm characterized by the presence of spindle cells with cigar-shaped nuclei, interlacing fascicles, and a whorled pattern. "Recently, MED12 mutation was reported in a high percentage of leiomyoma and has direct interactions with beta catenin, as does MED19." (PMID 23785396, 2013). "For example, MED12 down-regulation was identified in the comparison of tumors and normal tissue, while the Mediator complex and subunits MED4 and MED19 were specifically identified in the IPA analysis of the older black/older white comparisons of leiomyoma." (PMID 23785396, 2013). "Connecting with the PARP1 hub in leiomyoma from older black women were other genes involved in transcription or DNA repair including PRKDC, catenin (cadherin-associated protein), beta 1subunits, MED4, MED19 and MEDIATOR complex." (PMID 23785396, 2013).
lipodystrophy (1 paper, 2020). A congenital or acquired disorder characterized by abnormal loss or redistribution of the adipose tissue in the body. "Another example of ubiquitous gene expression changes in the pathogenesis of lipodystrophy is the knock-down of the MED19 subunit of the mediator transcription complex." (PMID 33233602, 2020). "Under systemic conditions in a mouse model, the adipocyte-specific MED19 knock-down in adipose tissue leads to lipodystrophy, hepatic steatosis and insulin resistance which is associated with a change in the PPARγ-mediated gene expression, but also with beiging of BAT." (PMID 33233602, 2020).
metastatic prostate carcinoma (1 paper, 2023). A carcinoma that arises from the prostate gland and has spread to other anatomic sites. "MED19 mRNA exhibits increased expression in primary and metastatic prostate cancer, correlating with a lower overall survival." (PMID 37880276, 2023).
prostate adenocarcinoma (1 paper, 2023). "Both isoforms were present in prostate adenocarcinoma, but canonical MED19 expression was more prominent (histoscore 4 + 3 for canonical MED19 and 3 + 2 for alternative MED19)." (PMID 37880276, 2023). "Our findings suggest that both isoforms are expressed at comparable protein levels during prostate development, and that canonical MED19 protein was expressed at a higher level than alternative MED19 in normal adult prostate and prostate adenocarcinoma." (PMID 37880276, 2023).
tongue cancer (1 paper, 2013). A malignant neoplasm affecting the tongue. "The effect of Med19 silencing in tongue cancer cell proliferation, tumor formation and cell migration was investigated in vitro and in vivo." (PMID 23705783, 2013). "Our research was the first report in which it has been demonstrated that Med19 modulates tongue cancer cell proliferation and migration and disruption of Med19 has antitumorigenic effects." (PMID 23705783, 2013). "The colony number of Med19 shRNA treated cells decreased from 166.0 ± 7.8 colonies/well in the control group to 124.0 ± 4.4 colonies/well in the Med19 shRNA lentivirus infected group in tongue cancer cells." (PMID 23705783, 2013). "Our results thus suggested that Med19 shRNA inhibited tongue cancer cells proliferation through modulating cell cycle progression." (PMID 23705783, 2013). "In this study, we investigated the antitumorigenic effects of lentivirus-mediated transduction of Med19 shRNA into tongue cancer cells by quantifying cellular proliferation, tumor growth, cell cycle and migration ability." (PMID 23705783, 2013). "In this way, we could conclude that knockdown of Med19 could inhibit cell migration of tongue cancer cells." (PMID 23705783, 2013). "We demonstrated that lentivirus-mediated Med19 knockdown could arrest tongue cancer cells at G1 phase, inhibit tongue cancer cell proliferation and migration in vitro." (PMID 23705783, 2013). "We then detected whether Med19 shRNA affected the proliferation ability of tongue cancer cells by MTT cell proliferation assay and BrdU incorporation assay." (PMID 23705783, 2013). "Med19 possibly plays a critical role in the migration of tongue cancer." (PMID 23705783, 2013). "Our results provide the evidence that lentivirus-mediated Med19 downregulation inhibits tongue cancer cell proliferation and tumorigenesis both in vitro and in vivo, suggesting that disruption of Med19 by lentivirus transduction may be a promising approach for tongue cancer therapy." (PMID 23705783, 2013). "Although it has been reported that Med19 plays an important role in stabilizing the whole mediator complex, its biological importance in tongue cancer cell proliferation and migration has not been addressed." (PMID 23705783, 2013). "However, the functional role of Med19 in tongue cancer cell growth and migration has not been reported." (PMID 23705783, 2013).